HPSE (heparanase)
Diseases named in the same sentence as HPSE in open-access papers (continued):
Sharing a sentence is not in itself a finding about the gene and the disease.
tumor (continued). "Based on its multiple activities, heparanase has been associated with a wide range of physiological and pathological processes, including tumor growth, angiogenesis, invasion and chemoresistance, inflammation, fibrosis, coagulation and thrombosis or viral infection." (PMID 32937952, 2020). "The fact that the T5 splice variant of heparanase, which lacks enzymatic activity and heparin binding capability, also enhances tumor growth and is associated with a poor prognosis raises the question as to the relevance of the enzymatic activity of heparanase in cancer biology." (PMID 31850210, 2019). "In tumor development, the degradation of heparan sulfate (HS) by heparanase (HPSE) is associated with cell-surface and extracellular matrix remodeling as well as the release of HS-bound signaling molecules, allowing cancer cell migration, invasion and angiogenesis." (PMID 30818840, 2019). "Interestingly, in vitro studies demonstrated the ability of this HS mimetic to strongly counteract receptor tyrosine kinase-mediated signaling and heparanase-induced expression of genes associated with tumor aggressive phenotypes." (PMID 30413079, 2018). "Given the increasingly recognized clinical significance of heparanase, the HS-specific endo-β-d-glucuronidase implicated in multiple aspects of tumor growth and progression, extensive efforts were made to identify agents targeting the HS-degrading activity of this enzyme." (PMID 30413079, 2018). "In addition, experiments using a variety of tumor cells and related animal models have found that high HPSE expression is associated with increases tumor cell metastasis and chemo-resistance." (PMID 28388549, 2017). "Moreover, heparanase expression in several tumor types (including breast) was linked to therapy resistance." (PMID 28038446, 2017). "Heparanase is associated with cell adhesion, matrix metabolism, tumor metastasis and angiogenesis." (PMID 28994624, 2017). "Importantly, increased heparanase levels are associated with reduced patients’ survival post operation and increased tumor aggressiveness." (PMID 28038446, 2017). "Sixteen studies evaluated associations between tumor size and HPSE expression." (PMID 28388549, 2017). "Heparanase expression is increased in many types of tumors and this elevation is frequently associated with more aggressive disease and poor prognosis, most often due to increased tumor metastasis." (PMID 27732945, 2016). "However, since mast cells also secrete large amounts of heparin, they are the cell type that is likely responsible for invasion-associated heparanase activity in the tumor microenvironment." (PMID 25734659, 2015). "Further, induction of A disintegrin and metalloproteinase with thrombospondin-type repeats-1 (ADAMTS1) has been related to angiogenic sprouting during wound healing, and elevated expression of heparanase (HPSE) in patients is associated with high levels of tumor-associated angiogenesis." (PMID 26393803, 2015). "Heparanase is implicated in angiogenesis and tumor progression." (PMID 25386347, 2014). "Estimation of the correlation between the color strength of the stain for heparanase and the risk of the disease recurring was performed on 55 patients with biopsy samples taken from a primary tumor following radical surgery to remove the tumor." (PMID 24887057, 2014).
tumor (continued). "In summary, this study suggests that the synthesized MAP vaccine based on B-cell epitopes of human HPSE is capable of attenuating human HCC metastasis in vivo, which is probably induced by suppressing HPSE activity and tumor associated angiogenesis, by virtue of the anti-MAP polyclonal antibodies." (PMID 23308126, 2013). "Heparanase is an endo-β-glucuronidase that cleaves heparan sulfate side chains, leading to structural modifications that loosen the extracellular matrix barrier and associated with tumor metastasis, inflammation and angiogenesis." (PMID 23028487, 2012). "The results in this study demonstrate that genetic alteration and reduction of HPSE expression are associated with tumor progression and poor prognosis of HCCs, suggesting that HPSE behaves like a tumor suppressor gene and is a potential prognostic marker for HCC patients." (PMID 22952874, 2012). "Heparanase is an endoglycosidase which cleaves heparan sulfate (HS) side chains at a limited number of sites, activity that is strongly implicated in cell dissemination associated with tumor metastasis, inflammation and angiogenesis." (PMID 21364956, 2011). "The upregulation of HPSE in many tumours has been linked to poor prognosis." (PMID 21285983, 2011). "Heparanase, a protein involved in regulating the transcription of inflammation-related genes, participates in promoting the persistence of inflammation status, release of inflammatory cell extravasation, tumor-associated growth factors and cytokines, and acceleration of tumor growth." (PMID 37291634, 2023). "However, the precise role of the NCRs and HS GAGs in NK cell tumor surveillance remains unclear since NKp30-dependent NK cell cytotoxicity was unaffected by GAG-deficiency or heparanase treatment of tumor cell targets." (PMID 31134055, 2019). "Upregulation of heparanase, the mammalian endoglycosidase devoted to HS degradation, is observed in essentially all tumor types examined, including carcinomas, sarcomas, and hematological malignancies where, in several cases, it is associated with an aggressive tumor behavior." (PMID 30413079, 2018). "The observation that human PDAC specimens overexpressing heparanase also show high levels of macrophage infiltration supports the clinical relevance of these findings and suggests a role for the enzyme in guiding the tumor-promoting action of tumor-associated macrophages." (PMID 30413079, 2018). "Thus, elevated levels of heparanase may activate syndecan family members and promote tumor metastasis and angiogenesis, resulting in poor prognosis often associated with patients exhibiting high levels of heparanase." (PMID 18545691, 2008). "Moreover, the pattern of expression of heparanase reveals the potential for localised degradation of tumour-associated HS, and release of active HS saccharide-growth factor complexes that could enhance the malignant phenotype." (PMID 17437011, 2007). "Its overexpression is strongly correlated with increased tumor growth, angiogenesis, metastasis, and inflammation, highlighting HPSE as a compelling therapeutic target for oncology and inflammatory diseases." (PMID 42215649, 2026). "Multiple studies have shown that HPSE overexpression correlates with enhanced metastatic potential across diverse tumor types." (PMID 41301515, 2025). "Conversely, inhibition of HPSE through gene silencing or selective inhibitors reduced the invasive capacity and metastatic spread of several tumor cell lines in both in vitro and in vivo models." (PMID 41301515, 2025). "Engineering CAR-T cells to express heparanase has been shown to improve their tumor-penetrating ability and enhance anti-tumor effects." (PMID 41281748, 2025). "We concluded that the ability of mAb 9E8 to inhibit the growth of Raji tumors is due to the neutralization of heparanase contributed by cells (i.e., macrophages) residing in the tumor microenvironment." (PMID 40940793, 2025).
tumor (continued). "Recent data suggest that the expression of HPSE promotes autophagy through a reduction in mTOR1, the key regulator of autophagy, by promoting tumor growth and chemoresistance." (PMID 41301515, 2025). "Highly sulfated heparin enhances antimetastatic and antiangiogenic activities through dual mechanisms: improved heparanase inhibition and more effective blocking of P-selectin-mediated tumor cell adhesion." (PMID 40143176, 2025). "PG545 treatment was also found to inhibit the expression of heparanase in the tumor tissue of the 4T1 model." (PMID 40723905, 2025). "HS remodeling enzymes, such as heparanase and sulfatases, play a significant role in the modification of HSPGs within the tumor microenvironment." (PMID 40564190, 2025). "A key mechanism by which heparanase accelerates cancer progression is by enabling the release and bioavailability of HS-bound growth factors, chemokines, and cytokines, residing in the tumor microenvironment and supporting tumor growth and metastasis." (PMID 40940793, 2025). "The results showed that the expression of HPSE was significantly elevated in tumor tissues in comparison to adjacent normal tissues." (PMID 39935175, 2025). "Compelling evidence implies that heparanase promotes essentially all aspects of the tumorigenic process, namely, tumor initiation, vascularization, growth, metastasis, and chemoresistance." (PMID 40940793, 2025). "Back in 2015, heparanase expressed by CAR-T lymphocytes was shown to improve their capability of tumor infiltration as well as their antitumor activity toward human neuroblastoma xenografts in mice." (PMID 39996879, 2025). "Though heparanase is not widely evaluated in all GEP-NETs, studies among PNETs demonstrated a direct correlation between high heparanase expression and advanced tumor grade and distant metastasis." (PMID 40565098, 2025). "In this regard, including ECM degradation enzymes like heparanase or inhibiting MMP proteins has been shown to enhance CAR-T cell trafficking by facilitating their movement through the dense tumor matrix." (PMID 40699720, 2025). "ECM-degrading enzymes like heparanase can improve tumor infiltration, and exosomes can be used to deliver therapeutic RNA or other molecules to enhance tumor responses." (PMID 40260240, 2025). "Experimental data demonstrate that targeted heparanase suppression effectively limits both tumor advancement and metastatic spread." (PMID 40143176, 2025). "In a preclinical study, heparanase-expressing CAR T cells demonstrated significantly improved tumor infiltration and antitumor activity in solid tumor models, with no observed increase in off-target effects." (PMID 41181132, 2025). "This suppresses VEGF-induced activation of cellular signal transduction in tumor endothelial cells and stops heparanase-mediated degradation of ECM, resulting in increased levels of these proteins in plasma (NCT01252095)." (PMID 39594665, 2024). "When degraded by heparanase, HS releases these bound molecules, which can stimulate cell motility and contribute to tumor cell migration." (PMID 39247596, 2024). "This was explained by the fact that blocking the interaction of growth factors and heparanase with HS in the tumor microenvironment leads to the release of free ligands into the plasma." (PMID 39594665, 2024). "In the realm of metastasis, tumor cells exhibiting heightened heparanase expression facilitate epithelial–mesenchymal transition (EMT), a pivotal process for hematogenous metastasis." (PMID 39459002, 2024). "Numerous clinical association studies have consistently demonstrated that upregulated heparanase expression correlates with increased tumor size, tumor progression, enhanced metastasis, and poor prognosis." (PMID 38334603, 2024). "Existing research has shown that AS101 downregulates the expression of heparanase, leading to the inhibition of tumor cell metastasis." (PMID 39247596, 2024).
tumor (continued). "Heparanase also releases angiogenic factors in the extracellular matrix, is overexpressed in tumor cells, and promotes tumor metastasis and angiogenesis." (PMID 39247596, 2024). "Heparanase is an enzyme that can upregulate the expression of TF through the disassociation of TFPI, and tumor cells that express heparanase are considered to have increased metastatic potential." (PMID 38893201, 2024). "Splice 36 functions as a dominant negative to wild-type heparanase, thereby suppressing HS degradation, tumor growth, and metastasis." (PMID 39202399, 2024). "The design allows for a controlled release of the drugs in the tumor in response to heparanase and uses monocytes to phagocytize the micelles and deliver them into the tumor." (PMID 38756653, 2024). "Heparanase promotes tumor progression via the PI3K/AKT/mTOR signaling pathway, which is specifically correlated with the phosphorylation of AKT and mTOR." (PMID 39247596, 2024). "Compelling evidence ties heparanase to all steps of tumor formation, including tumor initiation, growth, metastasis, and chemoresistance." (PMID 38334603, 2024). "Tumor invasion and metastasis are further promoted by the degradation of heparan sulfate in the extracellular matrix by heparanase." (PMID 39108793, 2024). "Heparanase can cleave heparan sulfate side chains to modify the extracellular matrix integrity, enhancing tumor cell invasion." (PMID 39128081, 2024). "In this way, heparanase profoundly shapes the tumor microenvironment affecting several cancer cell features." (PMID 39349458, 2024). "The results of this study indicate that AS101 inhibits tumor migration by downregulating heparanase through the AKT/mTOR signaling pathway and has positive effects in vivo." (PMID 39247596, 2024). "The correlation between its low epithelial expression and a high shed level in serum, which is mainly favored by dysregulated HPSE activity, indicates a high tumor stage with a low overall survival rate." (PMID 38655136, 2024). "HPSE is the main enzyme responsible for extracellular HS degradation and its expression is significantly increased in aggressive cancers, facilitating tumor progression through metastatic dissemination." (PMID 38655136, 2024). "Nuclear shuttling of HSP90 controls heparanase functioning and influences cell differences that shift tumor dormancy." (PMID 38994941, 2024). "Another strategy is the generation of CAR-T cells expressing enzymes against tumor stroma (e.g., heparanase) or chemokine receptors (e.g., CXCR1 and CXCR2) matching tumor chemokines and promoting infiltration." (PMID 38201305, 2024). "Our study indicated that downregulating the expression of heparanase with AS101 treatment significantly reduced the migration of mouse tumor cells in vitro and in vivo." (PMID 39247596, 2024). "Human NK cells that expressed low levels of heparanase induced their invasion into tumor and the ensuing tumor suppression." (PMID 39415291, 2024). "Heparanase (Hpa1) is expressed by tumor cells and cells of the tumor microenvironment and functions to remodel the extracellular matrix (ECM) and regulate the bioavailability of ECM-bound factors that support tumor growth." (PMID 38334603, 2024). "Heparanase, an enzyme that cleaves heparan sulfate proteoglycans in the extracellular matrix and basement membrane, facilitates tumor invasion and metastasis." (PMID 39677123, 2024). "In cancer, heparanase promotes tumor growth and metastasis by facilitating tumor cell invasion and angiogenesis through degradation of the extracellular matrix and the release of pro-angiogenic and growth-promoting factors." (PMID 39202399, 2024). "Despite negative margins after potentially curative resection, patients who express high levels of heparanase in their resected tumors have worse postoperative survival, suggesting that heparanase expression confers a more aggressive tumor phenotype." (PMID 38334603, 2024).
tumor (continued). "We found that heparanase is closely correlated with tumor metastasis and is overexpressed in several types of cancer." (PMID 39247596, 2024). "The importance of HS side chains in this function emerged from studies showing that by cleaving HS side chains, heparanase enhances histone acetyltransferase activity and elicits a more aggressive tumor phenotype." (PMID 38519456, 2024). "For this purpose, dicarboxylated oxy-heparins (DCoxHs) containing three carboxylate groups per split residue (DC-Hep) were prepared and examined for their heparanase-inhibiting activity and effect on tumor growth and metastasis in mouse models." (PMID 38334603, 2024). "This response leads to an elevation in heparanase levels, a crucial regulator of metastases and interactions within the tumour microenvironment, the heightened levels of which serve as an indicator of a poor prognosis in MM." (PMID 38397231, 2024). "Other procoagulant molecules expressed by tumor cells include heparanase, cancer procoagulant (CP), and podoplanin (PDP)." (PMID 38893201, 2024). "Heparanase (HPSE) is an endoglycosidase and has the ability to degrade heparan–sulphate proteoglycans, the main component of the tumor extracellular matrix, to remodel the extracellular matrix and promote the aggressiveness and chemoresistance of tumors." (PMID 36983174, 2023). "Remarkably, heparanase inhibitors were effective even when the xenografted tumor cells were devoid of heparanase, emphasizing the significance of heparanase contributed by cells residing in the tumor microenvironment." (PMID 37547889, 2023). "In fact, heparanase-1 enzymatic activity contributes to the tumor-promoting functions of the FGF through HS degradation and, under certain circumstances, through HS sulfation." (PMID 36680276, 2023). "PG545 (a synthetic heparan sulphate mimetic that decreases heparanase expression) created by Progen Pharmaceuticals has been shown to suppress tumor growth in MDA-MB-231 xenografts and inhibit angiogenesis in animal studies." (PMID 37759706, 2023). "The involvement of heparanase-1 in such crucial steps of primary tumor initiation and in close cooperation with key proto-oncogenes, as well as tumor suppressors, places the enzyme among the key pro-tumoral factors." (PMID 36680276, 2023). "It appears that targeting the tumor microenvironment by heparanase inhibitors enhances the antitumor activity of approved therapies, further providing a strong rationale for applying antiheparanase therapy in combination with conventional anticancer drugs." (PMID 37547889, 2023). "One of the most promising antitumor mechanisms of λ-COs reported involves the inhibition of heparanase (HPSE) activity, an enzyme strongly implicated in tumor progression and overexpressed in most cancers." (PMID 37233489, 2023). "It is known that HPSE has been recently shown to play a role in the autophagy of cancer cells, leading to chemoresistance and tumor progression." (PMID 37508554, 2023). "Subsequent studies provided compelling evidence that ties heparanase levels with all steps of tumor formation including tumor initiation, angiogenesis, growth, metastasis, and chemoresistance." (PMID 37547889, 2023). "In this way, heparanase mediates tumor–host crosstalk, and promotes basic cellular processes (i.e., exosome formation, autophagy, and immune responses) that together orchestrate tissue remodeling." (PMID 36980232, 2023). "Roneparstat (SST0001) is a 15–25 kDa N-acetylated and glycol split heparin with low anticoagulant activity and high anti-heparanase-1 activity with a potential anti-tumor role." (PMID 36680276, 2023). "A higher increase of autophagy was observed following HPSE overexpression in tumor-derived cells, with an enhancement of tumor growth and chemoresistance." (PMID 37508554, 2023). "Heparanase not only enhances tumor cell dissemination but also accelerates the growth of the primary tumor." (PMID 37547889, 2023).